RN7SL484P (RNA, 7SL, cytoplasmic 484, pseudogene)
Gene: Miscellaneous RNA gene on chromosome 15 (99,791,209 to 99,791,410, forward strand). Ensembl gene ENSG00000241588.
Homologues: Orthologues: chimpanzee Metazoa_SRP (95% identical), pig Metazoa_SRP (66% identical). Paralogues in human: RN7SL209P (92% identical), RN7SL185P (87% identical), RN7SL469P (87% identical), RN7SL495P (87% identical), RN7SL673P (87% identical), RN7SL545P (86% identical), RN7SL628P (86% identical), RN7SL719P (86% identical), RN7SL759P (86% identical), RN7SL82P (86% identical), RN7SL536P (86% identical), Metazoa_SRP (85% identical), and 709 more.